CXCL10 (C-X-C motif chemokine ligand 10)
Diseases named in the same sentence as CXCL10 in open-access papers (continued):
Sharing a sentence is not in itself a finding about the gene and the disease.
COVID-19 (continued). "Notably, CXCL10, a cytokine that is implicated among the three key players contributing to COVID-19 cytokine storm and increased fatal COVID-19 outcomes, was highly expressed in the COVID-19(+) TV group compared to the other disease groups." (PMID 37026002, 2023). "Elevated CXCL10 levels are associated with severe COVID-19 and worse progression." (PMID 37998327, 2023). "It is known that the increased level of CXCL10 is associated with COVID-19 severity." (PMID 37795081, 2023). "Furthermore, AMP5A suppresses a distinct set of pro-inflammatory cytokines (including IL-1β, IL-6, IL-12, and CXCL10) associated with COVID-19 and pro-inflammatory NF-κB activation." (PMID 35261923, 2022). "It has been proven that CXCL10 is associated with inflammatory diseases, including COVID-19." (PMID 35409036, 2022). "CXCL10 is a cytokine found in elevated level in both COVID-19 and cancer-causing cytokine storm." (PMID 36239108, 2022). "Moreover, high serum levels of cytokines, such as IL-6, CCL2, CXCL8, CXCL10, IL-2, and IL-10 were associated with COVID-19-related encephalopathy and showed an enhanced systemic inflammatory response." (PMID 36232655, 2022). "In both cases of cancer and COVID-19, CXCL10 exacerbates inflammation that causes tissue damage." (PMID 36239108, 2022). "In this sense, other cytokines and chemokines such as MCP-1, IL-10, IL-15, CXCL10, and CCL2 have been associated with SARS-CoV-2 viremia." (PMID 35783606, 2022). "This could be a critical observation because B-cells represent a potential source of pathogenic, TLR7/8 derived, CXCL10 following tissue damage in COVID-19 and could also be a drug target in our PBMC models." (PMID 35261923, 2022). "According to a study, the C-X-C motif 10 (CXCL10), or Interferon gamma-induced protein 10 is a notable cytokine molecule in the prognosis of COVID-19, which is capable of causing severe tissue damage and is also involved in pathological processes of infectious diseases." (PMID 36239108, 2022). "Moreover, CXCL10 was suggested to be a potential diagnostic and prognostic marker in several viral infections such as COVID-19." (PMID 36366543, 2022). "Association of anosmia and pulmonary involvement can be justified by the roll ofchemokines, as previous reports defined CXCL10 contribution in both cytokine storm of COVID-19 patients causing acute respiratory distress syndrome (ARDS) and demyelination process of the olfactory nerve causing anosmia." (PMID 34794467, 2021). "Although the in silico facts about the association of ACE2 and CXCL10 overexpression in lung cancer patients and COVID-19’s severe manifestations in these individuals coincide with peripheral relevant studies, further wet-lab experiments are required for in-depth understanding." (PMID 33585826, 2021). "Interestingly, we observed that sVCAM-1 was highly correlated with GM-CSF, the TH1 chemokine CXCL10 and IL-10, which our team and others recently identified as the peculiar “cytokine/chemokine signature” associated with poorer outcome in COVID-19 patients." (PMID 34422854, 2021). "We demonstrated that severe COVID-19 was associated with elevated levels of numerous plasma mediators indicative of coagulation, endothelial activation and a broad inflammatory response including CXCL10, GM-CSF, and IL-6." (PMID 33692097, 2021). "Finally, based on this systemic analysis, we concluded that ACE2 and CXCL10 are two possible biomarkers responsible for the higher susceptibility and fatality of lung cancer patients towards the COVID-19." (PMID 33585826, 2021). "Furthermore, several clinical studies reported that higher CXCL10 circulating levels are positively related with disease severity and increased risk of death in patients with COVID-19." (PMID 34224085, 2021). "High levels of hallmark cytokines associated with SARS-Cov2 infection such as CXCL10 and IL-6 could be detected in the nasal cavity of patients with mild COVID-19." (PMID 34581925, 2021).
COVID-19 (continued). "The results of these initial analyses provided primary evidence that overexpression of ACE2 receptor and enhanced CXCL10 cytokine expression might be the major possible reason for increased susceptibility and fatality of lung cancer patients towards COVID-19." (PMID 33585826, 2021). "Similarly, we determined 5999 genes that are co-altered with CXCL10 in the case of lung cancer development and 6430 co-expressed genes associated with COVID-19." (PMID 33585826, 2021). "In addition, we also recently reported that both plasma and alveolar CXCL10 concentrations were independently associated with the duration of mechanical ventilation in COVID-19 ARDS patients." (PMID 33272291, 2020). "Corticosteroids were shown to improve survival in severe COVID-19 patients in a recent therapeutic trial, and this may be linked to a decrease in CXCL10 levels, via the inhibition of the Th-1 pathway." (PMID 33272291, 2020). "It remains to be seen whether the inhibition of CXCL10 production from epithelial cells could have a therapeutic potential in selected COVID-19 patients at increased risk of severe disease, by limiting the infiltration of CXCR3+ immune cells into lung tissue." (PMID 33284849, 2020). "Additionally, CXCL-10 concentration was found to be a potential biomarker of neuroinflammatory reaction in the CSF samples from patients with neurological disorders associated with COVID-19." (PMID 39205221, 2024). "Low numbers of NK cells detected in the peripheral blood of patients with COVID-19 may also be due to the recruitment of pathogenic NK cells to the lungs in response to high levels of CXCL10, accompanied by their activation and the induction of IFN-γ production." (PMID 36768315, 2023). "Severe or fatal COVID-19 is indeed associated with elevated innate pro-inflammatory immune cytokines in peripheral blood including interleukin (IL)-1, IL-6, IL-8, or C–X–C motif chemokine ligand 10 (CXCL-10) and alterations of both innate and adaptive immunity." (PMID 34322128, 2021). "At Day 1, COVID-19 exhibited significantly higher IL-6, IL-10, and CXCL10; FluA showed an attenuated cytokine response." (PMID 41683886, 2026). "A significant increase in CXCL9 and CXCL10 chemokine levels was observed in samples from patients in the acute phase compared to the recovery phase of COVID-19." (PMID 41425601, 2025). "IFNγ, CXCL10, and IL-6 are among many elevated proteins at baseline in all COVID-19 positive subjects relative to healthy subjects." (PMID 40424310, 2025). "In COVID-19, markedly elevated CXCL10 levels are related to ARDS and neurological complications, such as the loss of smell and taste, and are a good biomarker of disease severity." (PMID 40980495, 2025). "In contrast, Epstein–Barr Virus (EBV) can lead to an increase in IL-6 and CXCL10, which are known to be correlated with COVID-19 severity." (PMID 40332501, 2025). "on whole lung transcriptome observed an increased induction of pro-inflammatory genes such as Saa3, Cxcl10, and Cxcl11 in both influenza and COVID-19 infected mice." (PMID 38911865, 2024). "In our series, the proportion of LRP1/CD91 expressing monocytes was reduced in severe cases and was inversely correlated with the level of CXCL10, selected as a representative cytokine in the storm observed in COVID-19 patient sera." (PMID 39136010, 2024). "On the other hand, CCL2 and CXCL10, elevated in severe cases, highlight the importance of chemokines in mediating immune responses and exacerbating lung injury in COVID-19." (PMID 39203987, 2024). "Beyond cytokines, some chemokines are also implicated in the severity of COVID-19, acting as chemoattractants for immune cells, such as CCL2 or CXCL10, which contribute to the amplification of the inflammatory response." (PMID 39916956, 2024). ", and systemic HG and, along with CXCL10/IP-10, these six nodes represent 58.4% of the total predictive capacity in submodel y2 in classifying COVID-19 severity at an accuracy of 91.2%." (PMID 38617584, 2024).
COVID-19 (continued). "CXCL10 is a pro-inflammatory chemokine that plays a crucial role in the COVID-19-related cytokine storm and olfactory dysfunctions." (PMID 39024368, 2024). "And in agreement with our results, some studies have shown that CXCL10 levels decrease after COVID-19 vaccination." (PMID 39247198, 2024). "Expanding upon the significance of chemokines such as CCL2 and CXCL10 in severe COVID-19 cases, it is critical to understand their function in orchestrating the immune response, especially in lung injury and systemic inflammation." (PMID 39203987, 2024). "Further, it has been shown that the urine of COVID-19 patients contains increased levels of proinflammatory cytokines like IL-6, IL-8, and CXCL-10, and high urinary IFN-γ upon hospital admission proved to be a positive predictor of AKI in COVID-19 patients." (PMID 38398672, 2024). "There was a positive correlation observed between the levels of activated (CD69+) total ILCs and activated ILCp, as well as the levels of serum IL-6 and CXCL10 in patients with COVID-19." (PMID 38391948, 2024). "The persistence of high levels of IFN I and IFN III and proinflammatory cytokines, such as CXCL9, CXCL10, and IL-8, after COVID-19 recovery has been related to the development of LC." (PMID 38319477, 2024). "CXCL10, GM-CSF, VEGF, IL-1β and CCL2 were clearly positively associated with a higher COVID-19 severity in elderly patients even after adjustment for age and correction for multiple testing." (PMID 38715114, 2024). "We believe that the findings of our study, highlighting the association with the severity of COVID-19 and the high levels of GMCSF and CXCL10 and low levels of CD8+ TSCM, require further investigation and confirmation on a larger scale." (PMID 38715114, 2024). "Five chemokines were explored in this study, where 3 of them (MCP-1/CCL2, IL-8/CXCL8, and IP-10/CXCL10) showed a significant increase in COVID-19 patients with further increase in higher severities." (PMID 38855114, 2024). "We also demonstrated the distribution of the values found for neuroinflammatory biomarkers (cell count, protein concentrations, neopterin, and CXCL-10 in the CSF) with regard to the duration of COVID-19 symptoms in days." (PMID 39205221, 2024). "We found that a high level of the senescence-associated cytokines GM-CSF, CXCL10, VEGF and CCL2, NLR, and a high CD27−CD28− percentage among CD8+ T cells, were positively associated with increased COVID-19 severity." (PMID 38715114, 2024). "Both CCL5 and CXCL10 were reported to be predictive biomarkers for clinical outcomes of COVID-19, and it appears this observation can be broadly applied to other betacoronaviruses, including PHEV." (PMID 38932231, 2024). "Some chemokines were also elevated in patients with severe COVID-19, as chemokine ligand (CCL)-2 (CCL2), CCL3, and chemokine CXC ligands (CXCL), CXCL8, CXCL9, CXCL10, and CXCL11 the most associated with this clinical condition." (PMID 39281667, 2024). "The RNA expression of CXCL10 in hamster nasal tissue or COVID-19 patients’ BALF sample has been reported." (PMID 38483537, 2024). "Among these inflammatory mediators, we identified known markers of severe COVID-19, such as the monocyte-recruiting chemokine CXCL10 and DPP4." (PMID 39334742, 2024). "Among the many cytokines with significantly greater cumulative exposure in COVID-19 were CXCL10, CCL8, CCL2, IL-6, and TNF-α (q < 0.05, Mann-Whitney)." (PMID 38502186, 2024). "This classifier reinforced the prognostic importance of monocyte/macrophage, NK cell, and Th1-pathway activation, with prediction of severe COVID-19 driven by higher concentrations of IL-7, CXCL10, IL-15, and CXCL9, and lower concentrations of MDC and IL-5." (PMID 38368384, 2024). "In other words, the predictive capacity of systemic cytokine CXCL10/IP-10 is disproportionately higher than the other nodes in classifying COVID-19 diagnosis (submodel y1) relative to COVID-19 severity (submodel y2)." (PMID 38617584, 2024).
COVID-19 (continued). "There was an almost 50% greater decrease in the gene expression of the chemokine CXCL-10, an important driver of inflammation in COVID-19, in the OmeGo-treated group." (PMID 39000027, 2024). "CCL3, CCL5, CXCL2, and CXCL10 have been reported to be increased in patients with severe COVID-19-related acute respiratory distress syndrome (ARDS)." (PMID 38584257, 2024). "Two known markers of severe COVID-19 were identified among the soluble mediators modulated during Sulfodyne® treatment, CXCL10, and DPP4." (PMID 39334742, 2024). "Within these, inflammatory markers previously associated with COVID-19 severity were among the high-contribution features of the severity factor, including IL6, CXCL10, and CXCL8 (IL8) proteins in serum." (PMID 38690733, 2024). "Several cytokines (GM-CSF and IL-6) and chemokines (MCP-1/CCL2, IL-8/CXCL8, and IP-10/CXCL10) were markedly increased in COVID-19 patients with a significant correlation with disease severity." (PMID 38855114, 2024). "The lungs of patients with severe COVID-19 are abundant in highly inflammatory macrophages, which secrete inflammatory mediators like IL-1β, IL-6, IL-8, CXCL10, TNF-α, and other chemokines, further exacerbating the occurrence of cytokine storms." (PMID 37163438, 2023). "CXCL10 is considered a predictive biomarker of patient outcome in COVID-19, and increased levels are associated with ARDS and neurological complications of COVID-19." (PMID 37998327, 2023). "A study from Mexico reported elevated levels of MIG, MCP-1, and CXCL-10 in severe COVID-19 patients, consistent with our findings." (PMID 37685858, 2023). "The gene expression analyses have confirmed that CXCL10 was upregulated in the COVID-19 patients compared to their sex-and age-matched healthy counterparts." (PMID 37832397, 2023). "The immunoregulatory role CXCL10 has in exacerbating cytokine storm syndromes including COVID-19 has been commonly recognized." (PMID 38107402, 2023). "Our study reaffirms previous studies reporting increased IL-6, CXCL10 and IL-16 serum levels in patients with COVID-19 with BSI being a major bias." (PMID 36759861, 2023). "Significantly higher serum concentrations of CXCL10 and viral loads in patients with COVID-19 have been reported in patients with fatal disease than in survivors, and a CXCL10 levels are positively correlated with the SARS-CoV-2 viral load." (PMID 37493737, 2023). "Infections associated with COVID-19, however, have been associated with high serum levels of IL-6, CXCL8, and CXCL10." (PMID 37109156, 2023). "Our findings indicate that plasma levels of TSLP, IL-15, and CXCL10/IP-10 were elevated in COVID-19 patients over that of normal uninfected controls." (PMID 36851770, 2023). "We found that CXCL10 expression was downregulated in ncMono during severe COVID-19, and cell–cell communication analysis inferred that the cellular interactions involving ncMono and plasmacytoid dendritic cells (pDC) were reduced in severe COVID-19." (PMID 37095364, 2023). "The primary aim of this study was to investigate the association between mortality and the CXCL9, CXCL10, CXCL11, and CXCR3, chemokine levels, which contribute to the pathogenesis of COVID-19 through hyperinflammation, in patients with COVID-19." (PMID 37493737, 2023). "In the subset of pregnant women with active COVID-19 during sample collection, CXCL-10 and IFN-γ were found to be significantly elevated compared to COVID-19 negative pregnant women." (PMID 37915987, 2023). "CXCL10/IP-10 has a well-established role in the COVID-19-related cytokine storm, and is involved in development of severe lung impairment." (PMID 36633406, 2023). "When comparing COVID-19 positive pregnant women to COVID-19 negative pregnant women, we found that only the serum level of CXCL10 was significantly up-regulated in the COVID-19 positive group." (PMID 37915987, 2023).
COVID-19 (continued). "Compared with the control group, there was extensive cytokine/chemokine correlations centered on IL-17A, IL-10, IL-6, CCL2, CXCL8, CXCL9 and CXCL10 and fewer correlations with IL-1β in the COVID-19 patients at baseline." (PMID 37662953, 2023). "We and others have reported that CXCL-10, the most prominently elevated cytokine in COVID-19 patients in this study, is a useful inflammatory marker related to COVID-19." (PMID 37685858, 2023). "CXCL10 was found to be up-regulated in COVID-19(+) TV skin in comparison to COVID-19(+) PU and COVID-19(-) PU skin in our study." (PMID 37026002, 2023). "This study confirmed that CXCL9, CXCL10, CXCL11, and CXCR3 levels are associated with disease severity in patients with COVID-19." (PMID 37493737, 2023). "In severe conditions of COVID-19, there is a high abundance of CXCL10+ and CCL2+ inflammatory macrophages that heavily express the GBP1 inflammatory gene." (PMID 38162574, 2023). "Strikingly, the four chemokines: Ccl2, Cxcl9, Cxcl10, and Cxl11, involved in the COVID-19 cytokine storm and found upregulated in both species in the present work, were also found to be overexpressed upon type I interferon application in vitro." (PMID 37350967, 2023). "We recently showed that patients with NAFLD have higher levels of IL-6, IL-8, IL-10, and CXCL10, and lower levels of IFN-γ, and these were associated with worse COVID-19 outcomes." (PMID 37375073, 2023). "Other studies have also indicated severity associated with increased levels of plasma chemokines, such as CCL2, CXCL8, and CXCL10, in severe COVID-19." (PMID 37632046, 2023). "We report downregulated cell transitions from classical monocytes to ncMono in COVID-19 with reduced CXCL10 expression in ncMono in severe disease." (PMID 37095364, 2023). "A more substantial 10-fold increase in CXCL-10/IP-10 was observed in hospitalized COVID-19 patients compared with healthy controls." (PMID 36851770, 2023). "Gene expression matrix for the 14 gene Cxcl10 up-regulated cluster and top single cell RNAseq correlations to four human COVID-19 studies." (PMID 38107402, 2023). "The levels of various chemokines in the circulation have been examined in patients with severe and critical COVID-19, and CXCL10 levels have been described as biomarkers that are positively correlated with both disease severity and the risk of death." (PMID 37493737, 2023). "We next tested different combinations of the 4 cytokines for the prediction of disease death and found that the combination of SPP1, CCL18m and CXCL10 best discriminated between survival and death of patients with COVID-19 (AUC of 0.86)." (PMID 37917179, 2023). "Serum CCL2, CCL3, CCL7, CXCL9, CXCL10, IL-1β and IL-1Ra levels increased in critical COVID-19 patients (n = 11) when compared to both severe COVID-19 patients (n = 25) and moderate COVID-19 patients (n = 14)." (PMID 36941580, 2023). "Our previous study in a small set of COVID-19 patients revealed that CXCL-10 levels in severe cases were consistently two-fold higher than in mild/moderate disease." (PMID 37685858, 2023). "Like SPP1, CXCL10, and CCL2, whose plasma levels associate with COVID-19 severity, the plasma level of CCL18 was also found to be significantly different between patients with mild and critical COVID-19." (PMID 37917179, 2023). "Results showed that patients with COVID-19 who were admitted to intensive care units had higher concentrations of CXCL10, CCL2, and TNF-α compared to that in patients with milder infections." (PMID 37363730, 2023). "So far, research has shown that COVID-19 patients with NAFLD have a distinct cytokine profile including increased levels of IL-6, IL-8, IL-10, and CXCL10, all associated with a more severe clinical presentation." (PMID 37375073, 2023). "For example, a positive correlation was found between lungs and peripheral inflammation in relation to IL-6 (r = 0.53, p < 0.01) and CXCL-10 (r2 = 0.99, p < 0.0001) levels in COVID-19." (PMID 37632046, 2023).